SH3BP2 (SH3 domain binding protein 2)
Description:
Binds differentially to the SH3 domains of certain proteins of signal transduction pathways. Binds to phosphatidylinositols; linking the hemopoietic tyrosine kinase fes to the cytoplasmic membrane in a phosphorylation dependent mechanism.
Synonyms: 3BP-2; 3BP2; RES4-23; CRBM; CRPM
Tractability: Small molecule: a structure with a bound ligand is known. PROTAC: ubiquitination databases record sites on it; its protein half-life has been measured.
Gene: Protein-coding gene on chromosome 4 (2,793,020 to 2,841,291, forward strand). Ensembl gene ENSG00000087266.
Subcellular location (Human Protein Atlas): Golgi apparatus
Gene Ontology:
Molecular function: phosphotyrosine residue binding; protein binding
Biological process: signal transduction
Genetic constraint (gnomAD): Loss-of-function variants: 38 observed, 51.97 expected, observed/expected ratio (o/e) 0.73, 90% interval 0.56 to 0.96. The upper end of that interval is the gene's LOEUF score, 0.96, which puts it in group 4 of 6, group 1 being the genes least tolerant of losing a copy. Missense variants: 748 observed, 758.16 expected, observed/expected ratio (o/e) 0.99, 90% interval 0.93 to 1.05. Synonymous variants: 346 observed, 318.74 expected, observed/expected ratio (o/e) 1.09, 90% interval 0.99 to 1.19.
Homologues: Orthologues: chimpanzee SH3BP2 (99% identical), mouse Sh3bp2 (87% identical), guinea pig SH3BP2 (86% identical), rat Sh3bp2 (86% identical), pig SH3BP2 (86% identical), dog SH3BP2 (86% identical), macaque SH3BP2 (83% identical), rabbit SH3BP2 (81% identical), tropical clawed frog sh3bp2 (50% identical), zebrafish sh3bp2 (43% identical).
Diseases named in the same sentence as SH3BP2 in open-access papers:
SH3BP2 is named in the same sentence as 37 diseases in open-access papers, as found by Europe PMC text mining. Sharing a sentence is not in itself a finding about the gene and the disease. The quoted sentences say what the papers report.
cherubism (32 papers, 2006 to 2025). Cherubism is a rare, self-limiting, fibro-osseous, genetic disease of childhood and adolescence characterized by varying degrees of progressive bilateral enlargement of the mandible and/or maxilla, with clinical repercussions in severe cases. "Gain-of-function missense mutations in the SH3BP2 gene have been identified as the cause of cherubism, which is an autosomal dominant disorder characterized by facial swelling owing to severe craniofacial bone destruction and subsequent fibrous tissue masses." (PMID 40134437, 2025). "Cherubism is caused by mutations in the SH3BP2 gene, which plays a role in regulating bone growth and remodeling." (PMID 40136761, 2025). "Cherubism is a rare genetic disorder caused mainly by gain-of-function mutations in the SH3BP2 gene, resulting in osteolysis of the jaws." (PMID 39951467, 2025). "This systemic inflammation is rescued when SH3BP2 KI mice are crossed with mice deficient in either TNF-α or MYD88 (a mediator of toll-like receptor signaling) indicating that cherubism is an auto-inflammatory bone disease." (PMID 41019663, 2025). "The causative role for SH3BP2 in cherubism has been confirmed in a mouse model harboring a P416R knock-in mutation (KI) in murine SH3BP2 (equivalent to P418R in humans)." (PMID 41019663, 2025). "Isolated cherubism is an autosomal dominant condition and caused by heterozygous missense variants in SH3BP2, mainly affecting codons 415 and 418–420 and causing a gain-of-function effect." (PMID 38374468, 2024). "Dentofacial abnormalities associated with cherubism stem from mutations in the SH3BP2 gene, which plays a crucial role in regulating osteoblasts and osteoclasts." (PMID 38638793, 2024). "Cherubism is known as a very rare autosomal dominant familial disorder of childhood caused by a mutation in the SH3BP2 gene on 4p16.3." (PMID 38902663, 2024). "It has been reported that single missense mutations in the SH3BP2 gene cause cherubism, a rare hereditary syndrome associated with severe craniofacial developmental defects in children." (PMID 36911671, 2023). "Dysregulation of the E3-ubiquitin ligase RNF146-mediated degradation of the adaptor protein 3BP2 (SH3 domain-binding protein 2) causes cherubism, an autosomal dominant disorder associated with severe inflammatory craniofacial dysmorphia syndrome in children." (PMID 36911671, 2023). "Gain-of-function missense mutations in the SH3BP2 gene cause cherubism, an autosomal dominant disorder associated with severe inflammatory craniofacial dysmorphia syndrome in children." (PMID 36911671, 2023). "It was found that SH3BP2 mutations in Cherubism result in the formation of hyperactive osteoclasts via activation of NFATc1 (Lietman, Kalinchinko, Deng, Kohanski, & Levine, 2006)." (PMID 35757898, 2022). "Gain-of-function missense mutations in the SH3BP2 gene are associated with cherubism, a rare hereditary syndrome characterized by severe craniofacial developmental defects in children." (PMID 35362478, 2022). "SH3 domain-binding protein 2 (SH3BP2) is a pathogenic gene of Cherubism and some studies have suggested that its protein was helpful to regulate the signaling pathway of B cells and macrophages in the immune system." (PMID 33996564, 2021). "Cherubism is a rare autosomal dominant disease caused bya mutation in the SH3-domain binding protein 2(SH3BP2) gene." (PMID 33470282, 2020). "Recent genetic and biochemical studies have provided critical insights into the pathogenic mechanism of cherubism thanks to the creation of knock-in (KI) mouse models with the most common SH3BP2 mutations." (PMID 30236129, 2018). "In vivo, Sh3bp2 KI mice develop systemic inflammation as a result of systemic infiltration by macrophages into tissues, as well as bone loss, defining cherubism as an auto-inflammatory bone disease." (PMID 30236129, 2018). "At the molecular level, cherubism is caused by mutation of the SH3BP2 gene (SH3 domain-binding protein 2), located on chromosome 4p16.3." (PMID 30236129, 2018).
cherubism (continued). "CGCL-like lesions of the jaws are the hallmark of cherubism, an autosomal dominantly inherited condition caused by mutations in the Sh3bp2 gene." (PMID 25681371, 2015). "Since then, mutations in the SH3BP2 gene have been identified in approximately 80 percent of people suffering from cherubism." (PMID 25093864, 2014). "Previously we have reported that gain-of-function mutations in SH3BP2 are responsible for cherubism (OMIM#118400)." (PMID 25144740, 2014). "We have introduced a P416R SH3BP2 mutation (equivalent to the most common P418R mutation in cherubism patients) into the mouse genome and established a knock-in (KI) mouse model for cherubism." (PMID 25144740, 2014). "Mutations in SH3BP2 result in osteoclasts that lead to increased bone resorption in jaws of cherubism patients, whereas in a mouse model bone resorption is more general." (PMID 22640988, 2012). "The limited distribution of bone lesions in patients with cherubism is unexpected as the disorder is associated with the heterozygous germline mutations in SH3BP2, which is widely expressed throughout the osteoimmune system." (PMID 22640988, 2012). "Most patients with cherubism have germline mutations in the gene encoding SH3BP2, an adapter protein involved in adaptive and innate immune response signaling." (PMID 22640988, 2012). "The familial form of cherubism occurs typically in an autosomal dominant trait with mutations in the SH3-domain binding protein 2 (SH3BP2) on chromosome 4p16.3." (PMID 22640403, 2012). "Before its identification as the principal disease-causing gene for cherubism, SH3BP2 had been of interest to immunologists because of its multiple roles in hematopoietic and immune cells." (PMID 22640988, 2012). "In this study, we identified a missense mutation at the SH3BP2 gene in a Chinese family with multiple affected individuals with cherubism." (PMID 17147794, 2006). "Cherubism is a rare genetic disorder caused by SH3BP2 mutations." (PMID 39951467, 2025). "Cherubism is a rare autosomal dominant disorder caused by mutations in the SH3BP2 gene." (PMID 35757898, 2022). "Cherubism is a rare autosomal dominant genetic condition caused by mutations in the SH3BP2 gene." (PMID 32825821, 2020). "Cherubism is a rare autosomal dominant disorder of the jaws caused by mutation of the SH3BP2 gene." (PMID 30236129, 2018). "Cherubism originates from genetic alteration in the SH3BP2 gene, and currently, it is believed to be caused by a gain-of-function mutation in the gene coding a c-Abltyrosine kinase-binding protein (SH3BP2) located on the short arm of chromosome 4." (PMID 30180903, 2018). "Gain-of-function mutations in SH3BP2 cause cherubism, characterized by jawbone destruction." (PMID 25144740, 2014). "They suspect that the trigger for cherubism in patients that are heterozygous for a Sh3bp2 mutation could be a hyper-reactive host response to oral pathogens or physical damage that occurs on a regular basis in the oral cavity." (PMID 22640988, 2012). "Gene testing is recommended to determine whether a mutation in the cherubism gene SH3BP2 is present and to confirm the clinical diagnosis of cherubism." (PMID 22640403, 2012). "In most patients, cherubism is due to dominant mutations in the SH3BP2 gene on chromosome 4p16.3." (PMID 22640403, 2012). "A missense mutation was identified in exon 9 of the SH3BP2 gene in patients with cherubism." (PMID 17147794, 2006). "A gain-of-function mutation in the SH3 domain-binding protein 2 (SH3BP2; MIM 602104) on chromosome 4p16.3 has been reported to cause cherubism." (PMID 39201553, 2024). "Cherubism (OMIM #118400) is a rare autosomal dominant genetic condition caused by mutations in the SH3BP2 gene, encoding for an adaptator protein, SH3BP2." (PMID 32825821, 2020).
cherubism (continued). "Missense mutations in SH3BP2 result in SH3BP2 that is stable, as it escapes the destructive actions of ARTD5 and ARTD6, and are associated with cherubism, a hereditary childhood-onset autoinflammatory disorder, whose severity regresses after puberty." (PMID 31590342, 2019). "In 1999, however, the distinct genetic basis for cherubism was mapped to chromosome 4p16.3 and the SH-3 binding protein SH3BP2." (PMID 25093864, 2014). "In the present study, we aimed to disentangle the impact of IL-1β in a Sh3bp2 KI mouse model of cherubism and determine whether IL-1β could be a novel therapeutic target to rescue the bone phenotype." (PMID 39951467, 2025). "Cherubism (CBM), characterized by expansile jawbones with multilocular fibrocystic lesions, is caused by gain‐of‐function mutations in SH3 domain‐binding protein 2 (SH3BP2; mouse orthologue Sh3bp2)." (PMID 35079675, 2022). "In order to definitively diagnose cherubism in our subject, attempts (in two separate laboratories, in Korea and in Israel) were made to amplify the corresponding mutations in the SH3BP2 gene in all 12 DNA samples, regardless of the extraction method used." (PMID 25093864, 2014). "In a few instances patients have been clinically diagnosed with cherubism but no mutation in SH3BP2 has been found, suggesting the possibility of genetic heterogeneity." (PMID 22640403, 2012). "However, other reports have shown that cherubism may occur without familal history suggesting either de novo mutations in SH3BP2 or genetic heterogeneity." (PMID 24608212, 2014). "Moreover, isoforms of SH3BP2 carrying cherubism mutations further increased NFAT and TRAP activation and therefore these mutant forms may be a sufficient stimulus to induce the osteoclastic bone lesions of cherubism in a manner consistent with a gain-of-function mutation." (PMID 22640988, 2012).
Osteopenia (6 papers, 2012 to 2022). Osteopenia is a term to define bone density that is not normal but also not as low as osteoporosis. "Specifically, SH3BP2 is produced in osteoblasts, and SH3BP2-deficient mice are reported to exhibit osteopenia due to the dysregulation of osteoblast differentiation and maturation." (PMID 30813388, 2019). "A mouse model carrying a Pro416Arg mutation in SH3BP2 develops osteopenia and expansile lytic lesions in bone and some soft tissue organs." (PMID 22640988, 2012). "Analysis of the SH3BP2 cherubism mutant mice revealed that heterozygous mice exhibit osteopenia owing to increased osteoclast formation, whereas homozygous mutant mice spontaneously develop systemic organ inflammation and severe osteopenia." (PMID 30813388, 2019). "In Sh3bp2 KI models, the observed osteopenia is due to an osteoblast functional defect and a reduction in OPG synthesis." (PMID 30236129, 2018).
Arthritis (5 papers, 2014 to 2021). Inflammation of a joint. "This concept is also supported by our previous findings that SH3BP2 deficiency suppresses the induction of collagen-induced arthritis." (PMID 33920631, 2021). "The improved phenotypes in the lupus model were opposite to the aggravated phenotypes caused by the Sh3bp2 gain-of-function mutation in murine arthritis models, which we had previously reported." (PMID 31052273, 2019). "We had previously reported that a gain-of-function mutation in SH3BP2 exacerbates inflammation and bone loss in murine arthritis models." (PMID 31052273, 2019). "Previously, we had reported the involvement of SH3BP2 in the pathogenesis of autoimmune arthritis, with an Sh3bp2 gain-of-function mutation aggravating joint inflammation and destruction in murine arthritis models." (PMID 31052273, 2019). "Effects of the Sh3bp2 gain-of-function mutation on disease processes in the lupus model differed from those observed in previous arthritis models." (PMID 31052273, 2019). "In a TNF-transgenic arthritis model, SH3BP2 deficiency decreased joint destruction via direct suppression of osteoclastogenesis." (PMID 31052273, 2019). "The Sh3bp2 gain-of-function mutation rescued lupus phenotypes while exacerbating joint inflammation and destruction in murine arthritis models." (PMID 31052273, 2019). "To investigate if P416R SH3BP2 heterozygous mutation affects the development of arthritis, we immunized Sh3bp2+/+ (n = 15) and Sh3bp2KI/+ (n = 14) mice with chick CII in complete Freund’s adjuvant." (PMID 25144740, 2014). "In the present study, we investigated a role of SH3BP2 in inflammatory bone loss in an arthritis model that requires adaptive immune responses." (PMID 25144740, 2014). "Also, we have previously reported that SH3BP2 deficiency suppresses antibody production against type II collagen and markedly prevents the development of arthritis in a collagen-induced arthritis model." (PMID 33920631, 2021). "Additionally, we also have reported that SH3BP2 deficiency suppresses pathogenic antibody production in a murine arthritis model." (PMID 33920631, 2021). "We had previously shown that SH3BP2 deficiency dramatically suppresses the production of anti-type II collagen antibody without affecting T cell response to type II collagen in a collagen-induced arthritis model." (PMID 31052273, 2019). "We have previously reported that in a collagen-induced arthritis model, SH3BP2 deficiency suppresses the development of arthritis by reducing the production of anti-type II collagen antibody, which was the first evidence showing the involvement of SH3BP2 in an autoimmune disease model." (PMID 33920631, 2021). "The severity of arthritis was significantly higher in arthritic Sh3bp2KI/+ mice compared with arthritic Sh3bp2+/+ mice at day 35–42 (12.83±1.02 in Sh3bp2KI/+ vs. 8.07±0.94 in Sh3bp2+/+ at day 42)." (PMID 25144740, 2014). "The differential effects of Sh3bp2 gain-of-function mutation between arthritis and lupus models might be attributed to the distinct pathological impact of TNF under arthritis and lupus conditions." (PMID 31052273, 2019). "Indeed, we previously reported that in murine arthritis models, SH3BP2 gain-of-function mutant mice exhibit more severe inflammation and bone destruction compared with wild-type mice." (PMID 30813388, 2019). "The incidence of arthritis at day 42 was comparable between Sh3bp2+/+ and Sh3bp2KI/+ mice (73.3% vs. 71.4%, respectively), although Sh3bp2KI/+ mice showed a tendency of earlier development compared with Sh3bp2+/+ mice (P = 0.13 at day 28 and P = 0.14 at day 31)." (PMID 25144740, 2014). "We utilized Sh3bp2KI/+ mice as an SH3BP2 gain-of-function model, because reduction in survival rate in Sh3bp2KI/KI mice due to severe systemic organ inflammation hinders the long-term observation of arthritis." (PMID 25144740, 2014). "Although the heterozygous Sh3bp2KI/+ mice do not develop arthritis, expression of SH3BP2 protein is elevated in Sh3bp2KI/+ BMMs." (PMID 25144740, 2014).
bladder cancer (4 papers, 2020 to 2021). "However, its role in cancer is still unclear, several studies have found that SH3BP2 was a protective factor and may be a tumor suppressor gene in bladder cancer." (PMID 33996564, 2021). "There is no report on the roles of OLR1, PGF, or SH3BP2 in outcomes of bladder cancer." (PMID 33888644, 2021).
gastrointestinal stromal tumor (4 papers, 2018 to 2024). "Active KIT mutations other than KITD816V are generally found in gastrointestinal stromal tumors (GISTs), and so the purpose of this study was to analyze the role of SH3BP2 in other KIT oncogenic mutations associated with pathology." (PMID 29885053, 2018). "Previously, our group established a relationship between the KIT receptor de-adaptor molecule SH3BP2 and the microphthalmia-associated transcription factor (MITF) in mast cells and gastrointestinal stromal tumors (GIST)." (PMID 36834926, 2023). "Among these genes, silencing of SH3BP2 could affect the growth of gastrointestinal stromal tumors." (PMID 38801557, 2024). "A previous study showed that silencing the adaptor molecule SH3 Binding Protein 2 (SH3BP2) reduced oncogenic KIT and PDGFRA receptor levels and impaired gastrointestinal stromal tumor (GIST) growth." (PMID 36551682, 2022).
autoimmune disease (2 papers, 2019 to 2021). A disorder resulting from loss of function or tissue destruction of an organ or multiple organs, arising from humoral or cellular immune responses of the individual to their own tissue constituents. "Our current findings warrant further research on developing a novel therapeutic approach to autoimmune diseases by modulating the expression of SH3BP2." (PMID 33920631, 2021). "Our findings offer better insight into the unique immunopathological roles of SH3BP2 in autoimmune diseases." (PMID 31052273, 2019). "Modulating SH3BP2 expression could thus provide a novel therapeutic approach to autoimmune diseases." (PMID 33920631, 2021). "However, it has not been determined whether and how the SH3BP2 deficiency suppresses the development of autoimmune diseases other than rheumatoid arthritis." (PMID 33920631, 2021).